AMY1A (amylase alpha 1A)
Description:
Calcium-binding enzyme that initiates starch digestion in the oral cavity. Catalyzes the hydrolysis of internal (1->4)-alpha-D-glucosidic bonds, yielding a mixture of maltose, isomaltose, small amounts of glucose as well as small linear and branched oligosaccharides called dextrins.
Synonyms: AMY1
Tractability: Small molecule: a high-quality ligand is known; it belongs to a druggable protein family. Antibody: UniProt places it where antibodies can reach, with high confidence; UniProt predicts a signal peptide or a membrane-spanning region; its Gene Ontology location is reachable by antibodies, with medium confidence. PROTAC: a small molecule that binds it is known.
Target class: Enzyme; Hydrolase
Gene: Protein-coding gene on chromosome 1 (103,650,592 to 103,664,629, forward strand). Ensembl gene ENSG00000237763.
Subcellular location: Secreted
Subcellular location (Human Protein Atlas): Cytosol; Golgi apparatus; Predicted to be secreted
Pathways (Reactome):
Digestion and absorption: Digestion of dietary carbohydrate
Gene Ontology:
Molecular function: alpha-amylase activity; calcium ion binding; chloride ion binding; catalytic activity; cation binding
Biological process: oligosaccharide metabolic process; carbohydrate metabolic process
Cellular component: extracellular exosome; extracellular region
Genetic constraint (gnomAD): Loss-of-function variants: 2 observed, 1.7 expected, observed/expected ratio (o/e) 1.18, 90% interval 0.41 to 1.9. That is too few expected variants to judge how well the gene tolerates losing a copy. Missense variants: 5 observed, 15.46 expected, observed/expected ratio (o/e) 0.32, 90% interval 0.17 to 0.68. Synonymous variants: 2 observed, 7.01 expected, observed/expected ratio (o/e) 0.29, 90% interval 0.12 to 0.9.
Homologues: Orthologues: macaque AMY2B (94% identical), tropical clawed frog amy2a (77% identical), tropical clawed frog amy2b (75% identical), Drosophila melanogaster Amy-p (53% identical), Drosophila melanogaster Amy-d (52% identical), Caenorhabditis elegans C50B6.7 (47% identical), Drosophila melanogaster Amyrel (47% identical), Drosophila melanogaster Mal-A7 (16% identical), Drosophila melanogaster Mal-A4 (15% identical), Drosophila melanogaster Mal-B2 (14% identical), Drosophila melanogaster Mal-A2 (14% identical), Drosophila melanogaster Mal-A8 (14% identical), and 3 more. Paralogues in human: AMY1B (100% identical), AMY1C (100% identical), AMY2B (97% identical), AMY2A (97% identical), SLC3A1 (17% identical), GBE1 (15% identical), SLC3A2 (13% identical).
Diseases named in the same sentence as AMY1A in open-access papers:
AMY1A is named in the same sentence as 7 diseases in open-access papers, as found by Europe PMC text mining. Sharing a sentence is not in itself a finding about the gene and the disease. The quoted sentences say what the papers report.
Alzheimer disease (2 papers, 2020 to 2025). A progressive, neurodegenerative disease characterized by loss of function and death of nerve cells in several areas of the brain leading to loss of cognitive function such as memory and language. "Four DMRs in Braak III vs. Braak 0 fell within dark regions of Alzheimer's disease risk genes (ABACA7, AMY1A, CHRFAM7A, CR1)." (PMID 41235755, 2025).
diabetes (1 paper, 2013). "The remaining non-calcium ion channel genes in the sternohyoid, Slc16a3, Amy1a, Chrnd and Ltbp1 did not have changed expression in previous studies of diabetes." (PMID 24199937, 2013).
oral cancer (1 paper, 2025). "In particular, AMY1A is involved in oral cancer, and most lung tumors that produce amylase have been identified histologically as adencarcinomas." (PMID 40869249, 2025).
cardiovascular diseases (1 paper, 2013). "For example, the ADIPOQ, AMY1A, CFB, HP and HBB are associated with the metabolic diseases, while the FBP4, HP, LPL and MYL2 are related to the cardiovascular diseases." (PMID 24204599, 2013).
tumor (1 paper, 2022). "Almost no tumor cell was identified as acinar cells, in accordance with the scarce expression of acinar genes (e.g., AQP5, NKCC1, AMY1A)." (PMID 35860547, 2022).
AMY1A also shares sentences with these, for which no sentence is quoted: cancer (1 paper); metabolic disease (1).